TERT (telomerase reverse transcriptase)
Diseases named in the same sentence as TERT in open-access papers (continued):
Sharing a sentence is not in itself a finding about the gene and the disease.
tumor (continued). "Interestingly, while it is also known that a larger primary tumour is associated with metastatic risk, only patients with TERT-altered tumours had larger primaries when contrasting to patients without TERT/ATRX alterations (Two-sided students t-test, p<0.05)." (PMID 38978571, 2024). "In contrast, in the patient showing re-induction of RAI uptake following treatment with larotrectinib, her tumor was negative for TERT promoter mutations and showed high TDS with no downregulation of the apical iodide transporter (SLC5A8) and the sodium–iodide symporter (SLC5A5) gene expression." (PMID 38642578, 2024). "For cancer types with no or marginal associations for these alleles/haplotypes, TERT-related mechanisms might be more heterogeneous and dependent on cell specificity, tumor subtype, and timing, as well as the type and intensity of environmental exposure." (PMID 39802763, 2024). "As TERT promoter mutations did not impact the prognosis of our miFTC/miOTC patients, other tumor groups might be more suitable for mutational screening, such as larger tumors with vascular invasion." (PMID 39363120, 2024). "This suggests that creating TERT that lacks catalytic activity could potentially enhance the formation of memories without the risk of tumor formation." (PMID 38421107, 2024). "Some articles have reported that the incidence of TERT promoter mutations is approximately 7.5-27% in PTC, and the mutation is correlated with particularly aggressive clinicopathological parameters, such as extrathyroidal extension, larger tumor size, and lymph node metastases." (PMID 36817603, 2023). "Since TERT-amplification showed to be an independent risk factor for worse patients ́ survival in our subcohort of patients with pT1N0-3 tumor stage, future studies to evaluate the prognostic value of TERT in patients undergoing exclusively endoscopic treatment could be of great clinical value." (PMID 37848472, 2023). "In the past, it has been suggested that TERT could be modulating the tumor microenvironment." (PMID 37085672, 2023). "Here we show that survival benefit is predicted by high B cell tumor infiltrate together with high TERT expression, but not tumor mutational burden or neaoantigen burden, placing TERT as a key antigen in mediating local antitumor immunity and favorable clinical outcome in HNSCC." (PMID 36909826, 2023). "Interestingly, in cancer cells TERT could activate endogenous retrovirus and induce interferon response which also promote to establish a immunosuppression tumor microenvironment by inhibiting different kinds of T cell populations." (PMID 38111043, 2023). "Importantly, TERT expression levels did not influence the outcome of patients with low B cell infiltrate (P = 0.245), suggesting that the presence of B cells in the tumor microenvironment is a necessary complement to TERT overexpression in providing clinical benefit." (PMID 36909826, 2023). "However, it plays a key role in sustaining the unlimited replication potential of cancerous cells, suggesting that TERT expression levels may represent a specific tumor development biomarker." (PMID 36980987, 2023). "Additionally, high TERT expression was associated with higher CD8+ T effector scores and higher co-stimulation T-cell scores, indicative of abundant immune cell infiltration in the tumor microenvironment." (PMID 37575241, 2023).
tumor (continued). "There are several established prognostic factors in thyroid cancer, such as age, sex, tumor histopathology, tumor size, lymphovascular invasion, extrathyroidal extension (ETE), lymph node metastasis (LNM), distant metastasis, BRAF mutation, and TERT promoter mutation." (PMID 37383396, 2023). "Besides, the prognostic significance of a TERT promoter mutation in these two tumor types, PLNTY and diffuse LGG, MAPK-pathway-altered, has not been fully elucidated yet as well, and there are yet no guidelines to classify such tumors." (PMID 36647073, 2023). "However, most of these factors are aberrantly produced in tumour cells and are responsible for the activation of oncogenic pathways through the uncontrolled de-repression of several genes involved in cell growth and division, including TERT." (PMID 38033865, 2023). "In addition, TERT could regulate the tumor microenvironment by facilitating tumor angiogenesis, shaping the inflammation and immunosuppressive environment, as well as activating the cancer-associated fibroblasts." (PMID 37079315, 2023). "This enabled a unique evaluation of the iodine avidity in primary tumour tissue, resected lymph node metastases, and comparison of avidity to the expression of iodine-transport related proteins (NIS, TPO, TSHR and pendrin), as well as mutations in the TERT promoter and codon V600 of the BRAF gene." (PMID 37352166, 2023). "Furthermore, the association between TERT promoter and BRAFV600E mutations creates a unique mechanism for the amplification of TERT expression, which results in higher tumor aggressiveness, which may justify a more radical surgical approach." (PMID 36561503, 2022). "In addition, some tumor mutational signatures were reported to correlate with immunotherapy efficacy in GBM, such as PTEN mutation, MAPK pathway‐associated gene alteration, and TERT mutation." (PMID 35822692, 2022). "Overall TERT promoter mutations were more frequent in tumours negative for HPV infection." (PMID 35804458, 2022). "TERT promoter mutations in tissue samples did not correlated with tumor size." (PMID 35311090, 2022). "Similarly, TERT can bind NF-κB following nuclear import and modulate the expression of specific NF-κB-dependent target genes that orchestrate both cell-intrinsic and -extrinsic mechanisms of tumor progression." (PMID 35159075, 2022). "Notably, the only poor prognosis tumour with a median telomere length within the range of normal thyroids (ID#6), and with TERT promoter methylation and TERT expression, showed a high percentage of separated signal pairs, suggesting that telomere length of chromosome 5p was shortened." (PMID 35979662, 2022). "A recent large study involving 2500 matched tumor–control samples from 36 different tumor types suggests that whereas the telomere content of tumors with ATRX or DAXX mutations is increased, tumors with TERT modifications show a moderate decrease in telomere content." (PMID 35565379, 2022). "Studies using telomerase peptides as a vaccination approach showed that it may be used as an attractive target for novel immunotherapies against cancer, by CTLs that can recognize peptides derived from TERT and eliminate TERT-positive tumor cells in murine and humans." (PMID 36361679, 2022). "Notably, most of the tumours with co‐occurring events at TERT‐locus, and those with an acute and extensive TERT promoter methylation, showed short telomere lengths, fitting with our hypothesis." (PMID 35979662, 2022).
tumor (continued). "Thus, GABP links cell proliferation and TERT expression selectively in TERTp-mutant tumor cells, providing a partial mechanistic explanation for the long-standing observation that cell proliferation state is associated with telomerase activity levels across a wide spectrum of human cancers." (PMID 36130485, 2022). "In addition to the ETV6-NTRK3 gene fusion, PGR, TERT, DOT1L, KDM5A and LRP1B mutations may be passenger mutations that promote tumor progression." (PMID 36585729, 2022). "Thus, to exclude a possible underestimation, it may be worthy of re‐evaluating available TC genomic data to ascertain the frequency of structural TERT gene alterations in these tumours." (PMID 36394204, 2022). "However, this may also have the limitation of the presence of some tumor cell infiltration or infiltration of other cells of the tumor microenvironment and is a likely explanation for the detectable levels of TERT expression in these samples." (PMID 35267575, 2022). "Another example is the telomerase reverse transcriptase (TERT), which is aberrantly expressed via its promoter in approximately 90% of aggressive cancers and 73% of tumor cases and is able to upregulate telomerase activity in cancer cells leading to tumor growth." (PMID 35892709, 2022). "Together, these data revealed common features of GBM, including gain of chr.7 and loss of chr.10, lacking IDH1/2 mutations, high frequency of TERT promoter mutation, loss of critical tumor suppressors (e.g., PTEN and CDKN2A/CDKN2B), high frequency of PDGFA and EGFR amplification." (PMID 34987659, 2022). "Therefore, TERT mutations are closely related to higher TMB value and a unique tumor microenvironment, which may be the reason why TERT mutation becomes a potential biomarker for anti-CTLA4 therapy." (PMID 35903534, 2022). "However, evidence has recently accumulated that GABPA function may be context-dependent, and it acts as a tumor suppressor in several types of cancer, despite its stimulatory effect on TERT transcription." (PMID 35549739, 2022). "Besides TERT, other genes encoding telomerase holoenzyme complex proteins such as DKC1 (Xq28), which we identified significantly upregulated in clinically aggressive tumours, and NHP2(5q35), are within the 5‐Mb‐ends of their respective chromosomes." (PMID 35979662, 2022). "TERT promoter mutation has not yet become the main pharmacological target for tumor therapy." (PMID 35135556, 2022). "For instance, NF-κB functions broadly during malignant transformation, tumor progression, and modulation of the tumor immune milieu; it also directly stimulates TERT expression and upregulates c-Myc, thereby potentiating the transcriptional effects of c-Myc on TERT." (PMID 35159075, 2022). "Meta-analysis was not performed for the association between TERT upregulation and secondary clinicopathological variables (extracapsular spread, tumor margins, perineural and lymphatic invasion), where a very low number of primary-level studies reported heterogeneous datasets." (PMID 35954336, 2022). "TERT promoter mutations are unique to tumor cells and do not exist in surrounding normal tissues; thus, any intervention that specifically targets its mode of operation may affect the survival of tumor cells." (PMID 35903534, 2022). "Similarly, we observed holistic TERT overexpression in tumor samples." (PMID 33924498, 2021). "In the 12 of 13 non-concordant samples, the TERT mutation was found in tumor but not in plasma." (PMID 33915518, 2021).
tumor (continued). "The TERT gene is a catalytic subunit of telomerase and plays an essential part in cellular immortality by maintaining telomere length at the end of chromosomes, which exhibited low or no expression in normal cells but highly expressed in 85%–90% of tumor cells and stem cells." (PMID 34950210, 2021). "Additionally, using pan-cancer analysis, we found similar variants of TERT promoter in CUP and NSCLC samples, suggesting that these mutations may serve as a diagnostic marker for identifying the primary tumour in CUP." (PMID 34302033, 2021). "In our study, MBCs harboring TERT genetic alterations had a tumor mutation burden (median 3.1 mutations/Mb; range 0.8–6.1) comparable to that of MBCs lacking genetic alterations affecting TERT (median 3.5 mutations/Mb; range 0.8–8.7; p = 0.72, Mann–Whitney U test)." (PMID 33863915, 2021). "Additionally, the presence of similar mutations of TERT promoter in CUP and NSCLC samples suggests these mutations may serve as a diagnostic marker for identifying the primary tumour in CUP patients." (PMID 34302033, 2021). "This strongly suggests that methylation of TERT may impact TERT abundance and tumour TL." (PMID 34824250, 2021). "A significant body of evidence has demonstrated that high levels of tumour TERT expression and/or telomerase activity are significantly associated with aggressiveness of disease, advanced clinical stage, and poor OS and/or DFS in several types of tumours, including UADT SCC." (PMID 34858860, 2021). "However, we noted that almost all recurrent PTCs without transformation in our study also had the TERT promoter mutation within the primary tumor." (PMID 33761111, 2021). "We have demonstrated that this theory of tumorigenesis with TERT promoter as the axis of genome evolution of UBC is supported by phylogenetic inference using CAPRI model based on custom heuristic optimization of cross-sectional genomic data of tumor specimens from multiple patients with UBC." (PMID 34395278, 2021). "Furthermore, individual tumor groups considering genetic and molecular subgroups (e.g., IDH and/or TERT mutation, 1p19q co-deletion, O6-methylguanine-DNA-methyltransferase [MGMT] status) should be investigated separately from each other in order to be able to go into more depth." (PMID 34677383, 2021). "Moreover, menin has been proposed as an important player in the regulation of various signaling networks associated to tumor development, such as the TGF-beta, RAS, Wingless type (Wnt) pathways—as well as influencing the expression of the telomerase reverse transcriptase (TERT) gene." (PMID 33269427, 2021). "Moreover, this cluster tumor is associated with amplified TERC, TERT, MYC, CCND1, and BCL2L1." (PMID 34815793, 2021). "TERT is the major rate-limiting catalytic subunit, which has a low/absent expression in normal cells but considerably high expression in the vast majority of tumor cells, suggesting that TERT expression level could be a specific biomarker for tumor development." (PMID 34746013, 2021). "Similarly, the tumors in non-HPV-related penile SCC tend to be larger than those in the HPV-related type, which may explain the correlation between TERT-p mutant type and larger tumor size." (PMID 33635430, 2021). "TERT promoter mutations might be an intrinsic key factor of tumor multistep progression, although it is not the sole driver of anaplastic transformation." (PMID 33761111, 2021). "However, some of the observations described in this and preceding papers imply that tumor promoting effects triggered by telomere damage in vivo may also involve the interconnected TERT and Terc compensatory response." (PMID 34736527, 2021).
tumor (continued). "TERT-p mutations were also more frequent in tumors with a lower histologic grade (p = 0.036), lower mitotic activity (p = 0.001), absence of necrosis (p = 0.045), larger tumor size (p = 0.045), and absence of lymph node or distant metastasis (p = 0.020)." (PMID 33635430, 2021). "Consistently with this critical pathogenic role, circulating cell-free TERT mRNA can be detected in plasma from cancer patients at levels that significantly correlate with those in tumor specimens, conversely, cell-free TERT mRNA is not detectable in plasma samples of healthy volunteers." (PMID 34746013, 2021). "Additionally, even when the tumor was not mutated the associated normal urothelium showed a TERT promoter mutation." (PMID 33562516, 2021). "Long-lasting responses were significantly associated with the absence of pre-vaccine endogenous TERT-specific tumor immunity, suggesting that long-lasting responses may only be observed in patients with low- or non-immunogenic tumors (unpublished data)." (PMID 33916194, 2021). "The TERT promoter status did not seem to segregate the risk of metastasis within any given histological grade, which was also supported by Kaplan−Meier curves stratifying for tumor grade (data not shown)." (PMID 34108637, 2021). "However, also in those cases, MD could still provide information on tumour molecular characteristics suggestive of aggressiveness (eg concurrent BRAFV600E and TERT variants)." (PMID 34505415, 2021). "In addition, these proteins are able to regulate TERT expression in tumor and normal cells." (PMID 33329574, 2020). "In addition, the increase in TERT expression may lead to the unlimited proliferative capacity of tumor cells, which is an important factor in tumorigenesis." (PMID 32810393, 2020). "Therefore, TERT mutations were closely related to a higher TMB value and unique tumor microenvironment, which may be the reason that TERT mutations may be a potential biomarker for anti‐CTLA4 treatment." (PMID 32810393, 2020). "Therefore, we hypothesized that TERT mRNA in the majority of these benign tumours, resulted from the presence of lymphocyte infiltration of the tumour sample." (PMID 32659948, 2020). "In addition, chemoresistant tumor cells can also upregulate TERT antigen." (PMID 32630460, 2020). "Thus, we have shown that DNA immunization with rat TERT induces a specific cellular and antibody response against its RT domain with a lytic potential, which may be harnessed to control tumor growth." (PMID 32570805, 2020). "Furthermore, the increased tumor incidence in Chk1 and Rrm2 transgenic mice could affect their survival, as is the case for TERT-overexpressing mice." (PMID 32253367, 2020). "In DTC and PTC, TERT promoter mutations were significantly associated with sex, age, tumor size, vascular invasion, extrathyroidal extension, lymph node and distant metastases, advanced tumor, nodes, and metastasis (TNM) stage, persistence/recurrence, and disease-specific mortality." (PMID 31655978, 2020). "TERT can directly regulate the various hallmarks of cancer, which include sustaining proliferative signaling, evading growth suppressors, inducing angiogenesis, resisting cell death, activating invasion and metastasis, tumor-promoting inflammation, and enabling replicative immortality." (PMID 33239622, 2020). "The finding that short-term TERT inhibition negatively impacts proliferation and viability of human malignant B cells xenografted in zebrafish embryos, both in the pre- and post-transplantation treatment approach, strongly enforces the validity of this strategy to counteract tumor growth." (PMID 32722398, 2020).